E2F1 (E2F transcription factor 1)
Diseases named in the same sentence as E2F1 in open-access papers (continued):
Sharing a sentence is not in itself a finding about the gene and the disease.
tumor (continued). "In tumours where MYCN, PRMT5 and E2F1 are expressed at lower levels and splicing activity is similarly reduced, we suggest that other PRMT5 independent mechanisms contribute to the malignant phenotype." (PMID 39021294, 2025). "Together with our recent finding that DDX5 augments deregulated E2F1 activity, activation of the DDX5 promoter by deregulated E2F1 suggests the presence of a feed forward loop in tumor suppressive E2F1 activity." (PMID 40869977, 2025). "Qiao’s team showed that Ubiquitin specific peptidase 11 (USP11) bound to E2F1 and promoted its stability by deubiquitination, and E2F1/USP11 formed a feedback loop to impede HCC tumor growth by inhibiting autophagy via activating ERK/mTOR pathway." (PMID 40221814, 2025). "Overexpression of E2F1 enhances tumor cell invasion and migration, whereas COA4 knockdown mitigates the malignant phenotypes induced by E2F1." (PMID 40936169, 2025). "Oncogenic regulators like E2F1 and MYC drive metastatic tumor environments and intertwine with immunoregulatory pathways, impairing T cell function and reducing immunotherapy effectiveness." (PMID 40299510, 2025). "We found that MYC, E2F1, and EIF4E are all positively correlated with PRMT5 and KRAS with an R-value > 0.70 and a p-value < 0.01 in CRC patient tumor samples." (PMID 40864819, 2025). "In this study, we report E2F1 as an upstream regulator of HMGCR, which is responsible for ferroptosis resistance of immune-edited tumor cells." (PMID 41339438, 2025). "Mechanistically, CsESPs upregulates E2F1, which subsequently activates CD24 transcription, ultimately promoting tumor cell proliferation while suppressing apoptosis." (PMID 40830893, 2025). "Six overlapping hub genes (CD8A, CDC20, E2F1, IL10, TNF, VCAM1) were overexpressed in GS 10 tumors, reflecting key pathways in tumor progression." (PMID 40227503, 2025). "The artificial promoters showed significantly higher cancer cell specificity compared to E2F1, hTERT, and ARF promoters, indicating that, by artificially modifying tumor suppressor gene promoters, we can enhance cancer cell-specific gene expression." (PMID 41439972, 2025). "For example, ICBP90, an E2F-1 target, recruits HDAC1 to promoter regions of various tumor suppressor genes, thus promoting tumor cell proliferation." (PMID 40701951, 2025). "ATAD5 gene is upregulated by activating E2F1, a key regulator of cell cycle progression, which promotes HBV replication and protects tumor cells from anticancer drugs." (PMID 38495502, 2024). "Our study illustrated the importance of RNH1 in LUAD and the potential regulation between E2F1 and RNH1 in the process of tumor formation." (PMID 38783241, 2024). "In line with this, NEAT1 was found to abrogate KDM5A expression via interacting with E2F1, which suppressed the KDM5A/H3K4me3-mediated repression of Cul4A expression, resulting in activated Wnt signaling pathway and augmented tumor formation." (PMID 39119602, 2024). "The IHC and ISH results for 40 BC tissues from the same tumour tissue microarray revealed that the level of hsa_circ_0007990 was correlated with the YBX1 protein (P = 0.027) and E2F1 mRNA (P = 0.038) levels, respectively." (PMID 38378679, 2024). "The Neurospora crassa mixture markedly blocked E2F1 transcription and downregulated lncRNA HOTAIR, thus exhibiting the anti-tumor impacts on cancer invasiveness and growth in vivo, while it had less effects on normal mammary cells." (PMID 39119602, 2024). "Immunohistochemistry confirmed that entrectinib treatment reduced the expression of STAMBP, E2F1, PDK1 and Ki-67 expression in tumor tissues." (PMID 39242557, 2024).
tumor (continued). "Mechanistically, AGPG physically activated E2F1 via interacting with PURα and blocking the binding of E2F1 to PURα, while AGPG inhibition significantly repressed tumor growth in the endocrine-resistant mouse model." (PMID 39119602, 2024). "Unexpectedly, the up-regulated miR-5100 target genes (CCNE2, E2F1, E2F2) had higher levels of expression in the tumor samples." (PMID 39590378, 2024). "To complete these observations, we stained and scored E2F1 and E2F8 protein expression in 154 tumor samples." (PMID 38686617, 2024). "SNORA38B plays a role in promoting tumor progression in NSCLC by directly binding to E2F transcription factor (E2F1) and regulating the GAB2/AKT/mTOR pathway thereby contributing to the development of an immunosuppressive tumor microenvironment." (PMID 38406265, 2024). "Prominent discoveries revealed heightened regulon activities of the E2F family (E2F1, E2F4 and E2F2), which are crucial in promoting tumour growth and migration." (PMID 39187937, 2024). "This decrease in tumor weight is primarily due to Bay’s effects on inhibiting the expression of genes regulating the cell cycle and cell proliferation, including CCND1, E2F1, CKS2, and Ki67." (PMID 38994944, 2024). "To evaluate the effects of MYBL2 knockdown on E2F1 overexpression or E2F7 knockdown in a more physiologically relevant setting, we performed tumor xenograft assays using genetically modified AGS sublines generated using the Tet-On system." (PMID 39613162, 2024). "We further showed the differences in malignant behavior of tumor cells after co-overexpression of RNH1 and E2F1." (PMID 38783241, 2024). "Our findings revealed that the TFs E2F1, HMGA1, MYC, FOSL1 and CREB3 exhibited exceptional levels of activity within C2 UBE2C+ tumour cells." (PMID 38894657, 2024). "Using machine learning approaches, including TreeBagger and DNN, and E2F1–8 expression datasets, survival terms of GBM patients were successfully predicted and validated, emphasizing that these factors play a key role in tumor progression and patient survival." (PMID 39061176, 2024). "E2F1, E2F3, and E2F4 are all transcription factor E2F family members, which are critical in controlling tumor-suppressor protein production and the cell cycle and are also targeted by small-DNA tumor virus transformation proteins." (PMID 37504265, 2023). "Therefore, we hypothesized that p20BAP31 induction of apoptosis was more sensitive in cancer cells, possibly because p20BAP31 inhibited the expression of E2F1, which in turn inhibits cancer cell proliferation by inhibiting the expression of tumor-related factors." (PMID 36977989, 2023). "This miRNA targets oncogenes and important genes for the initiation and progression of the tumor, including Myc, RAS, E2F1, E2F5, LIN28, ARID3B, PBX3, HMGA2 and long non-coding RNA H19." (PMID 36833380, 2023). "E2F1 is another core player involved in cell cycle progression, DNA damage response, and apoptosis; therefore, E2F1 inhibition may affect different levels of tumor development by blocking cell cycle progression and impounding the metabolic flexibility of cancer cells." (PMID 37965271, 2023). "Among the downregulated DEGs, the shared transcription factors include E2F4/DP1, E2F1/DP2, E2F4/DP2, and E2F1/DP1, which have been identified as important contributors to tumor progression in various cancer types." (PMID 38057925, 2023).
tumor (continued). "The expression of E2F1 and LINC01004 in tumor tissues of TCGA HCC patients was significantly positively correlated." (PMID 36721155, 2023). "Current studies demonstrate that the E2F family comprising E2F1 and E2F4 regulates the cell cycle tumour development and progression." (PMID 37779874, 2023). "TFs in XIST+ and S100A4+ tumor cells were similar, particularly RUNX3, REL, STAT4, and E2F1, which regulate the EMT process." (PMID 37430270, 2023). "We found that both E2F1 and EPHB2 expression is increased in tumor tissue compared to healthy lung and that high expression is associated with a trend towards worse prognosis, even if not reaching statistical significance." (PMID 37980331, 2023). "This study confirmed ECE2 as a downstream target gene of E2F1, while the effect of ECE2 on tumor progression was rarely illustrated." (PMID 36864456, 2023). "Results from our analysis also indicate that, among the thirty genes which are differentially expressed in OSCCs, seven of them (namely BRCA1, CCNE2, CDC25C, CDK1, CDK2, E2F1, and FANCD2) positively correlate with both tumor grade and HPV infection." (PMID 36768994, 2023). "Current research indicates that the E2F family, including E2F1 and E2F4, regulates cell cycle, tumorigenesis and progression of multiple tumours." (PMID 37779874, 2023). "Through direct regulation of cyclin D1 and E2F1 expression, ISX regulated the proliferation of tumour cells and their transforming activity." (PMID 37349365, 2023). "In recent years, numerous studies have found that pharmacological and genetic inhibition of E2F1 significantly inhibited tumor growth in CRC and E2F1 has also been revealed to participate in the metastasis and chemoresistance of CRC." (PMID 38062013, 2023). "Compared with silencing E2F1 alone, simultaneous silencing E2F1 and overexpressing CEP55 enhanced tumor growth." (PMID 35597996, 2022). "Overexpression of SIRT1 can induce cell cycle arrest via E2F Transcription Factor 1 (E2F1) and represses CRC proliferation and tumor initiation." (PMID 35328633, 2022). "To determine the in vivo relevance of our findings, we assessed tumor formation capacity in HK301 (E2F1-dependent) and HK408 (E2F1-independent) cell cultures transduced with shE2F1 or shControl (scrambled) lentivirus mediated gene expression targeting." (PMID 36213002, 2022). "The differential expression in GRNs identified in each patient also confirmed the tumor heterogeneity of SBA, with transcription factors (TFs) such as BATF, CREB3L1, KLF2, E2F1 variably expressed among different patients." (PMID 36104333, 2022). "MiR-532 directly targeted and inhibited E2F1 expression, leading to the decrease of ASK1 and elevation of TXNIP, and affected proliferation, cell cycle, apoptosis and DNA damage in vitro and tumor growth in vivo." (PMID 35440106, 2022). "The reduction of these genes in the R-PTP-κ-high group indicates that R-PTP-κ negatively regulates the expression of E2F1 target genes CCNE1 and CDC25A in various tumor tissues." (PMID 36551956, 2022). "TRPM2 is a potential therapeutic target to reduce tumor proliferation and increase doxorubicin sensitivity through modulation of FOXM1, E2F1, and cell cycle/DNA repair proteins." (PMID 35428820, 2022). "Gene group 2 displayed a significant upregulation of E2F transcription activators (E2F1, E2F2, E2F3, and E2F6) and tumor-specific transcription factors (MYCN, RUNX1, and GABPB1) in advanced Rb." (PMID 35626705, 2022). "Various studies have shown that lysine acetyltransferase 2A (KAT2A), E2F transcription factor 1 (E2F1), and ubiquitin conjugating enzyme E2 C (UBE2C) genes regulated the proliferation and migration of tumor cells through regulating the cell cycle." (PMID 36292703, 2022). "Several prior studies have shown that the transcription factor E2F1 can directly regulate TK1 and promote tumor proliferation." (PMID 36035114, 2022).
tumor (continued). "In transcriptome-based public datasets generated from four different tumor types, R-PTP-κ expression was negatively correlated with the expression pattern and prognostic value of two known E2F1 target genes (CCNE1 and CDC25A)." (PMID 36551956, 2022). "From the result of correlation analysis in tumor tissue samples across 11 cancer types and cell line samples in CCLE, we found that the correlation coefficient between the two in KAT2A, E2F1, and UBE2C was 0.037–0.82." (PMID 36292703, 2022). "Knockdown of SNHG12 blocked E2F1 recruitment and down-regulated the expression of CEP55, thereby inhibiting tumor formation and angiogenesis in nude mice." (PMID 35597996, 2022). "SEC61G was the center of the molecular network and targeting the E2F1/SEC61G pathway increased the expression level of MHC-I, which potentially in turn affects the difference in tumor drug sensitivity." (PMID 36712687, 2022). "Future studies are needed to determine if the E2F1-dependent induction of SREBP1 contributes to the expression of cyclin D1 and the inhibition of Rb in tumor cells." (PMID 36091143, 2022). "Altogether, these findings suggested that the inhibition of E2F1 reduced LINC00152 expression and consequently suppressed tumor growth in vivo." (PMID 35592867, 2022). "What is noteworthy is that Yang and his colleagues shed light on the role of E2F1 in facilitating cell cycle, in addition to augmenting PTC tumor growth and invasion." (PMID 35592867, 2022). "The developed inhibitors for E2F1 include the disruption of E2F1/DP1 binding by peptides or oligonucleotide decoys, but the main issue is the poor uptake by tumor cells." (PMID 36362068, 2022). "Unexpectedly, the correlation analysis between the upstream regulator's analysis identified MYBL2, E2F2, CBX3, FOXM1, and E2F1, which were significantly elevated in the LUAD or LIHC tumor groups, with a strongly correlated value with utility as biomarkers." (PMID 35404841, 2022). "The results demonstrated that the expression levels of CCNE1, E2F1, ARHGAP11A, RUNX1T1 and FES displayed significant correlation with the tumor stage in patients with NSCLC." (PMID 33613291, 2021). "Compared to sh‐NC + oe‐NC, transfection of sh‐E2F1 + oe‐NC in the cells reduced the expression of E2F1 and CCND1 in the tumor tissues." (PMID 34758200, 2021). "MiR-1205 is widely studied in tumors, in non-small cell lung cancer, miR-1205 exerts a tumor suppressor effect by cutting off the synergy between KRAS and MDM4/E2F1." (PMID 34180753, 2021). "Meanwhile, the expression of cell cycle-related genes such as E2F1, Cyclin D1, Cyclin B1, and CDK2 was also decreased after ITPR3 knockdown while P21, as a classical tumor suppressor gene was upregulated." (PMID 33573671, 2021). "In tumor cells, HNF4α downregulation leads to lnc‐APUE upregulation, which prevents the inhibition of miR‐20b on E2F1 expression and thereby promotes cell cycle progression and tumor growth." (PMID 33854885, 2021). "In an Ad5 backbone, the endogenous E1a promoter was replaced by the human E2F-1 promotor, which has a 5’ SV40 polyadenylation signal and promotes tumor-selective gene expression." (PMID 34123841, 2021). "The in vitro and in vivo assays suggested that PSMD14 depletion significantly impaired tumor growth, chemoresistance in HNSCC by antagonizing E2F1/Akt/SOX2 axis-mediated cancer cell stemness." (PMID 33456565, 2021). "Overexpression of E2F1 confers increased tumor sphere formation ability in MKN45 cell line, while E2F1 knockdown inhibits tumor sphere formation ability in 7901 cell line." (PMID 33986804, 2021). "Actually, previous researchers have identified lncRNAs as prognostic markers of PTC, such as TTTY10, LINC00284, RBMS3-AS1, and ZFX-AS1 and five lncRNAs of PPARG, E2F1, CCND1, JUN, and EZH2 for predicting tumor recurrence in PTC." (PMID 34721037, 2021).
tumor (continued). "In GE2-HCC, top potential transcriptional activators included transcription factors with reported tumour-promoting activity in HCC and/or other cancer types, e.g., NKX6-1, POU2F1/2, cJUN, E2F1, HSF2, SRF, TFCP2 and NFY." (PMID 33541355, 2021). "In this study, we found that THL dramatically suppressed the DUB activity of PSMD14 (with little effect on other JAMM DUBs) and E2F1/Akt/SOX2 pathway, which spurred tremendous interests to exploit THL as an anti-tumor drug." (PMID 33456565, 2021). "There are different regulatory axes in the same tumor, such as enhancing ESCC cell proliferation through miR-188-5p/PFN2 or interacting with miR-338-3P/miR-362-3p to activate E2F1 expression." (PMID 34372871, 2021). "Then we analyzed the correlation between transcription level of CCNE1, E2F1, ARHGAP11A, RUNX1T1, FES and tumor stage in TCGA NSCLC cohort by GEPIA 2 online website." (PMID 33613291, 2021). "In addition to controlling downstream gene transcription to promote tumour cell apoptosis and thus suppress cancer progression, E2F-1 is also actively involved in lipid metabolism in cells, and low-density lipoprotein-cholesterol can promote the expression of E2F-1 in endothelial cells." (PMID 34461908, 2021). "PP2A reduces the transcription of miR-9-3p and upregulates the expression of E2F transcription factor 1 (E2F1) by promoting the degradation of c-Myc, so it inhibits the apoptosis of tumor cells." (PMID 32175074, 2020). "In terms of DFS, patients with increased E2F1 (p < 0.001), E2F2 (p < 0.001), E2F7 (p < 0.001), and E2F8 (p = 0.001) tumor expression have a poorer prognosis." (PMID 33061852, 2020). "A significant reverse correlation was observed between the expression of E2F1 and MYCN mRNA and protein in OBP-301- and OBP-702-infected NB tumor cells." (PMID 32637577, 2020). "Among 12 candidate target genes, E2F1 and CCND1 were significantly downregulated by miR-93, and they were overexpressed in tumor tissues compared with matched adjacent normal tissues of clinical specimens." (PMID 32796817, 2020). "In MCF-7 cell lines, combination therapy enhanced the downregulation of essential components of the cell cycle (HMMR, AURKB, BIRC5) that control proliferative activities and tumour growth alongside downregulation of the anti-senescence markers FOXM1 and E2F1." (PMID 32787886, 2020). "The analysis of TCGA samples further confirmed the high expression of E2F1 and CCND1 in tumor samples." (PMID 32796817, 2020). "Deregulation of the validated miR-17~92 targets, including E2F1, TP53INP1, TGFβ and PTEN, is known to contribute to uncontrolled cell proliferation, tumor growth, apoptosis and metastasis 39,49." (PMID 32174776, 2020). "Collectively, we hold the opinion that miR-93 exhibited a tumor suppressor role by targeting E2F1 and CCND1, thereby inactivation of pRB/E2F1 pathway and AKT phosphorylation." (PMID 32796817, 2020). "In summary, our studies reveal a novel Sp1/E2F1/miR-203/Src pathway that is responsible for the activation of MMP2 and the tumor-promotive role of XIAP in BC cell invasion." (PMID 31811115, 2019).